LHFPL7 (LHFPL tetraspan subfamily member 7)
Synonyms: TMEM211; bA9F11.1
Tractability: Antibody: UniProt predicts a signal peptide or a membrane-spanning region.
Gene: Protein-coding gene on chromosome 22 (24,935,098 to 24,946,695, reverse strand). Ensembl gene ENSG00000206069.
Subcellular location: Membrane
Gene Ontology:
Cellular component: membrane
Genetic constraint (gnomAD): Loss-of-function variants: 9 observed, 11.25 expected, observed/expected ratio (o/e) 0.8, 90% interval 0.48 to 1.39. The upper end of that interval is the gene's LOEUF score, 1.39, which puts it in group 5 of 6, group 1 being the genes least tolerant of losing a copy. Missense variants: 130 observed, 171.56 expected, observed/expected ratio (o/e) 0.76, 90% interval 0.66 to 0.88. Synonymous variants: 68 observed, 66.08 expected, observed/expected ratio (o/e) 1.03, 90% interval 0.85 to 1.26.
Homologues: Orthologues: chimpanzee LHFPL7 (99% identical), pig LHFPL7 (76% identical), rabbit LHFPL7 (74% identical), dog LHFPL7 (73% identical), guinea pig LHFPL7 (70% identical), mouse Lhfpl7 (60% identical), rat Lhfpl7 (60% identical), macaque LHFPL7 (60% identical), tropical clawed frog lhfpl7 (40% identical), zebrafish si:dkey-35m8.1 (34% identical), Caenorhabditis elegans lhfp-4 (22% identical). Paralogues in human: LHFPL1 (24% identical), LHFPL6 (24% identical), LHFPL4 (22% identical), LHFPL5 (22% identical), LHFPL3 (21% identical), LHFPL2 (19% identical).
Diseases named in the same sentence as LHFPL7 in open-access papers:
LHFPL7 is named in the same sentence as 5 diseases in open-access papers, as found by Europe PMC text mining. Sharing a sentence is not in itself a finding about the gene and the disease.
LHFPL7 shares sentences with these, for which no sentence is quoted: cancer (1 paper); colon cancer (1); colorectal cancer (1); lymph node metastasis (1); tumor (1).